ENSG00000252824
Gene: Small nucleolar RNA gene on chromosome 7 (102,194,076 to 102,194,164, reverse strand). Ensembl gene ENSG00000252824.
Gene Ontology:
Biological process: RNA processing
Cellular component: nucleolus
Homologues: Paralogues in human: SNORA48 (89% identical), SNORA48B (88% identical).